SP1 (Sp1 transcription factor)
Diseases named in the same sentence as SP1 in open-access papers (continued):
Sharing a sentence is not in itself a finding about the gene and the disease.
tumor (continued). "In vivo, SP1 binds the 3′UTR of RNAs via its C2H2-ZNF domains, affecting the APA profile of numerous genes, suggesting that SP1 as an RBP may play a role in regulating tumor characteristics." (PMID 40290118, 2025). "By intervening at the level of SP1 condensation, this strategy may enable more selective modulation of transcriptional programs critical for tumor progression." (PMID 40884402, 2025). "The reintroduction of SP1 could partially reverse the apoptosis and ferroptosis of tumor cells induced by NPM1 knockdown." (PMID 39927464, 2025). "LncRNA SNHG12 could activate CDCA3 expression by stabilising SP1, thereby promoting tumour progression." (PMID 39999286, 2025). "In summary, these results suggest that, like its role in the embryonic microenvironment, SP1 might be involved in the expression of Plac1 during tumor initiation and progression." (PMID 40056047, 2025). "Anti-Sp1 approaches, such as transcriptional inhibitors or microRNA-based therapies targeting miR-382, a tumor suppressor gene, have demonstrated efficacy in preclinical models by suppressing tumor growth and metastasis." (PMID 40869407, 2025). "The current studies have confirmed that SP1 could bind to the promoter region thus activate transcription of its downstream genes to promote tumor progression 23-25." (PMID 38356702, 2024). "Animal experiments showed that SP1-knockdown obviously inhibited tumor growth in vivo." (PMID 38956367, 2024). "Several key signaling kinases, including extracellular signal-regulated protein kinases (ERK) one and 2, ataxia-telangiectasia mutated (ATM) kinase, JNK1, CDK2, PI3K, and Rad 3-related kinase, phosphorylate Sp1 to control proliferation, movement, and invasion of tumor cell." (PMID 39228402, 2024). "In HNSCC, Sp1 overexpression is also associated with tumor progression and is a negative prognostic factor." (PMID 38540340, 2024). "We also investigated whether depletion of SP1 could abrogate CAF-induced tumour burden in vivo in tumour cell–CAF orthotopic co-implantation models." (PMID 38429478, 2024). "Furthermore, c-Myc not only affects proliferation, apoptosis, and metabolism in tumor cells via its modification but also forms complexes with Sp1 on several promoters and titrates the levels of Sp1, thereby affecting the promoter activity of several genes." (PMID 38284882, 2024). "Next we investigated whether SP1 expression in PDAC tumours is dependent on the in vivo pH gradient." (PMID 38429478, 2024). "Moreover, AUNPs -SP1 significantly inhibited the tumor growth in vivo, by hindering SP1 expression and up-regulating GRYE-B." (PMID 37344887, 2023). "The protein level of Sp1 in tumour tissues was determined by immunohistochemistry." (PMID 37147632, 2023). "Also several study mentioned miR-133a as a tumor suppressor miRNA which inhibit the GC growth and exert its effect via different target genes such as Sp1, IGF1R, TCF4 and etc42–44." (PMID 37061507, 2023). "SP1 overexpression promoted tumor growth (group ov-SP1 vs. group vector)." (PMID 37686205, 2023). "Transcription factors Sp1/Sp3 are necessary for fetal development and tumor growth." (PMID 36759621, 2023). "SP1 knockdown significantly suppressed tumor growth, tumor size, and tumor weight." (PMID 36964266, 2023). "There is also extensive evidence that multiple compounds, including approved drugs that are used for other diseases, induce downregulation or degradation of Sp1, Sp3 and Sp4, which is accompanied by inhibition of cell/tumor growth and invasion and induction of apoptosis." (PMID 36982239, 2023).
tumor (continued). "Strikingly, both tumor-bearing mice with SP1 inhibitor injection and 4T1/ Rag GTPases KD cell xenografted tumors were endowed with slower tumor growth rates and much smaller sizes compared with control tumor-bearing mice." (PMID 37532694, 2023). "Interestingly, various reports have shown the over-expression of Sp1 in diverse types of cancer, relating its expression level to tumor stage and unfavorable prognosis for patient survival." (PMID 36520928, 2022). "SP1 promotes tumor growth, metastasis, and inhibits apoptosis of tumor cells." (PMID 35342417, 2022). "Besides its effects on tumor cells, Sp1 is also correlated with inflammation and immune cell infiltration." (PMID 35778451, 2022). "Plicamycin, also known as mithramycin A, is a natural polycyclic aromatic polyketide compound that inhibits SP1 transcription factor binding to DNA, which interferes with biological processes like tumour cell proliferation, apoptosis, angiogenesis, invasion, and metastasis." (PMID 36699463, 2022). "Moreover, SP1 transcriptionally upregulated circFAM126A, which further contributed the tumor growth and metastasis of OSCC." (PMID 35237504, 2022). "Interestingly, it has been reported that the expression of Sp1 in tumor cells induces the expression of diverse growth factors related to tumor growth and metastasis." (PMID 36520928, 2022). "SP1 can transcriptionally activate and repress numerous crucial oncogenes and tumour suppressors." (PMID 35485206, 2022). "In addition, treatment of the cells with MEDC (40 and 60 μg/mL) decreased Mcl-1 expression, which is a downstream target of Sp1, indicating that D. chinensis contains natural bioactive products that induce the apoptosis of tumor cells overexpressing Sp1." (PMID 35062995, 2022). "Our data also suggest that transcription factors such as CREB1 and ESR1 as well as pioneer factors such as PU.1 and Sp1 may contribute to the differentiation of MDSCs in the tumor." (PMID 36480485, 2022). "Therefore, the function and regulation of TIMP1 and Sp1 in immune cells can have a vital role in tumor pregression and aslo warrants further investigation." (PMID 35778451, 2022). "SP1 silencing suppressed the tumor growth, which was reversed by overexpression of KDM2A." (PMID 35508523, 2022). "Considering that both of the atypical E2Fs and SP1/SOX4/Anillin axis are involved in a similar HCC tumor process, we hypothesized some kind of relationship between these cell cycle regulating genes exists." (PMID 35924788, 2022). "Moreover, expression of Sp1 was upregulated in tumor-infiltrating MDSCs and was decreased in FcγRIIB KO MDSCs." (PMID 34976216, 2022). "Sp1 transcription factor regulates genes involved in various phenomena of tumor progression." (PMID 35163245, 2022). "Sp1 knockdown suppressed tumor progression by inhibiting AKT and ERK signaling." (PMID 35163245, 2022). "We therefore speculated whether FcγRIIB inhibition by Sp1 inhibitor might have a synergistic effect with gemcitabine to inhibit tumor progression." (PMID 34976216, 2022). "Moreover, bioinformatics analysis showed that Sp1 expression levels were positively correlated with that of DLAT in tumor tissues in TCGA data set." (PMID 35869499, 2022). "Furthermore, DHA evidently downregulated the expression of SP1 and hTERT on mRNA and protein level in tumor tissues." (PMID 34744749, 2021). "Furthermore, SP1 participated in tumor progression via regulating multiple downstream genes, such as vimentin, cadherin, E-cadherin, and CDK2." (PMID 33345272, 2021). "Specifically, we will show that KCNQ1OT1 and miR-124 mediate RB cell progression possibly via regulating SP1 expression and silent information regulator 1 (SIRT1)/c-Jun N-terminal kinase (JNK) signaling, which are strongly associated with tumor cell proliferation, apoptosis, and migration." (PMID 33345272, 2021). "Moreover, it has been found to sensitize tumor cells to TRAIL-mediated apoptosis via XIAP-gene promoter downregulation via its SP1 sites." (PMID 34381456, 2021).
tumor (continued). "As a consequence, SP1 is closely related to aggressive tumor behaviors and poor outcomes." (PMID 34257529, 2021). "A decreased level of SP1/miR-92b resulted in a restraint of in vivo tumor growth." (PMID 34905435, 2021). "This indicated that AFAP1-AS1 silencing led to a reduction in Sp1 protein levels in mouse tumor." (PMID 34145213, 2021). "In our present study, we identified that SP1 modulated the transcription of SNHG6, which demonstrated that SP1 could regulate the expression of tumor-associated proteins indirectly via lncRNAs." (PMID 33431838, 2021). "Additionally, transcription factors, including NF-κB, AP-1, and Sp-1, have been closely linked with MMP-9 expression in tumor cells." (PMID 33430488, 2021). "SP1 is the most highly represented member of tumor-related transcription factors." (PMID 33731131, 2021). "We hereby speculated that activation of the SP1/miR-92b loop generally promotes tumor progression in vivo." (PMID 34905435, 2021). "More importantly, SP1 was used to image tyrosine kinase in chick embryo chorioallantoic membrane and a HT-29 tumour-bearing mouse model, indicating that it could be used for real-time visualisation of tyrosine kinases in tumours." (PMID 34163615, 2021). "Furthermore, it was the first to verify SP1 correlated with clinicopathological parameters and poor prognosis in neoplasm." (PMID 34257529, 2021). "We used these groups to investigate the role of the AFAP1-AS1/miR-2110/Sp1 axis in tumor formation." (PMID 34145213, 2021). "Targeting either SP1 or miR-320a may be a potential strategy to prevent MACC1-driven tumor progression." (PMID 33731131, 2021). "After 28 days, the tumor volume of the mice delivered with cells overexpressing miR-363 mimic was much smaller than that of the control group, while the overexpression of circ0005654 and sp1 inhibited the effect of miR-363 and elevated tumor volume." (PMID 34499009, 2021). "However, more thorough researches are essential to validate the correlation of SP1 with tumor prognosis." (PMID 34257529, 2021). "In an attempt to test whether the combination therapy apart from targeting MDSCs and macrophages can foster the CSC killing, CD133 and SP1 gene expression was measured in the tumor sections revealing a significant decrease in both." (PMID 34381456, 2021). "Database prediction has shown that SP1 might be a potential target of HIF-1α's regulation, suggesting the function of HIF-1α in promoting tumor development and metastasis may through the regulation of SP1." (PMID 31892989, 2020). "Finally, we demonstrated that pretreatment of PTC-209 in mice bearing pemetrexed-resistant A549 tumors sensitized them to pemetrexed treatment and the expression of Ki-67, BMI1, and SP1 expression in tumor tissues was observed to be reduced." (PMID 32726929, 2020). "Additionally, MMP-9 expression in migratory and invasive tumor cells is thought to be regulated by transcription factors NF-κB, AP-1, and Sp-1, which are located in its promoter region." (PMID 32708058, 2020). "SP1 knockdown inhibited 143B tumour growth in nude mice (P < .01)." (PMID 32743904, 2020). "In addition, after overexpression of Sp1 or overexpression of miR-212-3p in tumor cells, their supernatants (also called conditioned medium) were collected and subjected to HUVECs." (PMID 33187481, 2020). "The expression and function of SP1 varies in different tumor cells." (PMID 31892989, 2020). "Patients with high expression of both HIF-1α and SP1 were more likely to have tumor metastasis." (PMID 31892989, 2020). "In summary, we demonstrated for the first time that long noncoding RNA SNHG12 could upregulate the expression of CDCA3 by stabilising the transcription factor SP1 and thereby promoting tumour progression and sunitinib resistance in RCC." (PMID 32641718, 2020). "Thus, SP1-derived orthografts represent a clinically relevant model for an in vivo CRISPR/Cas9 screen to identify novel genes/pathways that influence tumour response to docetaxel." (PMID 33033111, 2020).
tumor (continued). "Thus, it is suggested that knocking down or inhibiting the levels of Sp1 in OC cells can decrease tumor formation, tumor growth, and metastasis." (PMID 32050495, 2020). "Similar, ZLM-7 could inhibit tumor growth and angiogenesis through the miR-212-3p/Sp1/VEGFA axis in vivo." (PMID 33187481, 2020). "Finally, western blotting showed JP3 treatment up-regulated expression of TRIM25 and down-regulated expression of SP1 significantly in GC tumor tissues compared to the Ctrl-P-H treatment." (PMID 32576271, 2020). "Similarly to SOX9, the tumor progression driver SP1 is also a key factor for the induction of TGF-β during inflammation and its overexpression in Cyp51 knock-outs relates to EMT." (PMID 33182326, 2020). "For RCC, we also cannot rule out the possibility that signaling pathways mediated by other targets, apart from SP1, may play an important role in miR-362-3p-mediated anti-tumor effect." (PMID 32432112, 2020). "However, multivariate analyses indicated that tumor differentiation and high expression of both SP1 and LOXL2 were independent poor prognostic factors for DFS." (PMID 30976063, 2019). "Consistently, knockdown of FABP5, SP1 or both could all abolish the tumor-promoting effected induced by PA to similar extent." (PMID 30948929, 2019). "Besides, Sp1 plays an extremely important role in growth and metastasis of many tumors by regulating oncogenes, tumor suppressor genes, cell cycle control molecules, growth-related signal transduction, angiogenesis related factors, as well as apoptosis." (PMID 31614732, 2019). "By analyzing the expression of SP1 protein in TSCC patients with different genotypes, we found that the expression of SP1 protein in tumor tissues of patients with the deletion mutation was significantly higher than that of patients with the insertion mutation." (PMID 31270251, 2019). "In conclusion, knockdown of SP1/Syncytin1 axis inhibited the progression of NSCLC by the reversion of tumor epithelial‐mesenchymal transition process and suppression of Akt and Erk signaling pathways, suggesting that they are potential targets for targeted therapy of NSCLC." (PMID 31397118, 2019). "Based on the finding of a relevant fraction of ERG/Sp1 co-regulated genes among the ERG activated targets in ERG-fusion positive tumor, we tested the activity of a novel DNA binding and Sp1 interfering compound, demycarosyl-3D-β-D-digitoxosyl-mithramycin SK (EC-8042), in ERG positive models." (PMID 31143708, 2019). "Our study connects two hot research areas of tumor, namely, non-coding RNA and FA metabolism together and elucidates a new molecular mechanism underlying the PA induced GC metastasis via FABP5/SP1/UCA1 signaling which contributes to efficient prevention and therapeutic strategies for GC." (PMID 30948929, 2019). "In conclusion, our study demonstrated that miR‐1258 was down‐regulated in OSCC and may function as a tumour suppressor by targeting SP‐1, which consequently inhibited OSCC growth and metastasis." (PMID 30734471, 2019). "Western blots were used to detect the expression of SP1 protein in tumor tissues of TCSS patients." (PMID 31270251, 2019). "In addition, NAB2 upregulation in EGF-treated FaDu cell diminishes EGR1 transcriptional activity, resulting in the upregulation of Sp1-dependent tumor-promoting genes." (PMID 30845713, 2019). "In addition, STRAP inhibits Sp1-dependent transcription, resulting in the downregulation of the tumor suppressor genes E-cadherin and p21Cip1, thereby promoting tumor progression in non-small-cell lung cancers." (PMID 29849900, 2018). "In cervical cancer, MIR-296 functions as tumor suppressor via targeting SP1." (PMID 30474556, 2018).
tumor (continued). "Specificity protein 1 (Sp1), a member of the Sp/Krüppel-like factor transcription factor family, regulates multiple cellular functions and promotes tumor progression by regulating cell cycle, apoptosis, and metastasis, via binding to GC-rich sequences of the target genes’ promoter regions." (PMID 29348684, 2018). "In addition, elevated SP1 expression was detected in tumours, whereas low SP1 expression was detected in stromal cells and normal glandular cells surrounding the tumours." (PMID 28165192, 2017). "This strategy was used to generate a conditionally replicating virus containing the GaLV FMG under regulation of the MLP, with E1 expression controlled by a tumor-selective promoter containing eight E2F-binding sites and one specificity protein 1 (Sp1)-binding, designated ICOVIR16." (PMID 28106842, 2017). "Previous studies have shown that abnormal Sp1 activation might augment the growth and metastatic potential of tumor cells through over-expression of many Sp1 downstream genes." (PMID 28192510, 2017). "On the other hand, Sp1 has been reported to be overexpressed in some tumors, indicating that Sp1 may play an important but different role in tumor development through regulation of down-stream target genes in different cell types." (PMID 29212263, 2017). "Furthermore, immunohistochemistry was used to detect SP1 in same GC patients’ paired tumor and normal tissues." (PMID 28569779, 2017). "Sp1 and Sp2 made up 39.59 and 22.44% of the tumor cells respectively." (PMID 28148223, 2017). "Studies have reported that activation of Sp1 plays a promotive role in tumor angiogenesis." (PMID 27806345, 2016). "Genes regulated by Sp1 might be better targets for combating tumors and their expression in tumor cells in response to heavy ion irradiation should be analyzed." (PMID 27047795, 2016). "Also, Sp1 is considered as a vital transcription factor for many genes due to regulation of multiple functions, including tumor cell survival, growth, angiogenesis, abnormal Sp1 expression." (PMID 26744613, 2016). "We discovered an inverse relationship between miR-29c and Sp1/MGMT levels in tumor samples." (PMID 27384876, 2016). "Sp1 deregulation might be beneficial for tumor cells and its overexpression is known to induce apoptosis of untransformed cells." (PMID 26868017, 2016). "Therefore, exploring how Sp1 is aberrant activated is of great importance for the understanding of tumor progression." (PMID 27806345, 2016). "Here, we investigated whether ING4 could inhibit Sp1 transcriptional activity to exert its suppressive effect on tumor angiogenesis." (PMID 27806345, 2016). "Recently, evidence suggested that Sp1 may promote tumor growth by regulating the function of COX2, whose expression was also elevated in PDAC and correlated with pancreatic cancer cell proliferation and migration." (PMID 27057636, 2016). "Importantly, genetic as well as pharmacological targeting of Sp1 was able to reduce tumor growth both in vitro and in vivo, thus indicating that Sp1 is a suitable target for therapeutic intervention in MM and WM." (PMID 26771806, 2016). "Because HDAC inhibitors are known to preferentially induce caspase-8 activation to contribute to tumor cell death, we asked whether panobinostat induces caspase-8-dependent Sp1 protein degradation in MM cells." (PMID 27738323, 2016). "In this study, our results suggested that radiation combined with starvation might enhance the ability of surviving tumor cells to metastasize by regulating the expression of SP1." (PMID 27058528, 2016). "This suggests that sequestration of Sp1 could be one of the avenues to enhance sensitivity of tumor cells to alkylating generating drugs." (PMID 27384876, 2016).